NLK (nemo like kinase)
Description:
Serine/threonine-protein kinase that regulates a number of transcription factors with key roles in cell fate determination. Positive effector of the non-canonical Wnt signaling pathway, acting downstream of WNT5A, MAP3K7/TAK1 and HIPK2. Negative regulator of the canonical Wnt/beta-catenin signaling pathway. Binds to and phosphorylates TCF7L2/TCF4 and LEF1, promoting the dissociation of the TCF7L2/LEF1/beta-catenin complex from DNA, as well as the ubiquitination and subsequent proteolysis of LEF1. Together these effects inhibit the transcriptional activation of canonical Wnt/beta-catenin target genes. Negative regulator of the Notch signaling pathway. Binds to and phosphorylates NOTCH1, thereby preventing the formation of a transcriptionally active ternary complex of NOTCH1, RBPJ/RBPSUH and MAML1. Negative regulator of the MYB family of transcription factors. Phosphorylation of MYB leads to its subsequent proteolysis while phosphorylation of MYBL1 and MYBL2 inhibits their interaction with the coactivator CREBBP. Other transcription factors may also be inhibited by direct phosphorylation of CREBBP itself. Acts downstream of IL6 and MAP3K7/TAK1 to phosphorylate STAT3, which is in turn required for activation of NLK by MAP3K7/TAK1. Upon IL1B stimulus, cooperates with ATF5 to activate the transactivation activity of C/EBP subfamily members. Phosphorylates ATF5 but also stabilizes ATF5 protein levels in a kinase-independent manner. Acts as an inhibitor of the mTORC1 complex in response to osmotic stress by mediating phosphorylation of RPTOR, thereby preventing recruitment of the mTORC1 complex to lysosomes.
Tractability: Small molecule: a high-quality ligand is known; it belongs to a druggable protein family. PROTAC: it is named in the literature on targeted protein degradation; ubiquitination databases record sites on it; a small molecule that binds it is known.
Target class: CMGC protein kinase group; CMGC protein kinase MAPK family; Enzyme; Kinase; CMGC protein kinase nmo subfamily; Protein Kinase
Gene: Protein-coding gene on chromosome 17 (28,041,723 to 28,196,381, forward strand). Ensembl gene ENSG00000087095.
Subcellular location: Nucleus; Cytoplasm
Subcellular location (Human Protein Atlas): Nucleoplasm; Cell Junctions; Nucleoli
Pathways (Reactome):
Signal Transduction: Ca2+ pathway
Gene Ontology:
Molecular function: DNA-binding transcription factor binding; protein binding; protein serine kinase activity; protein serine/threonine kinase activity; ubiquitin protein ligase binding; ATP binding; magnesium ion binding; MAP kinase activity; protein kinase activity; SH2 domain binding
Biological process: cellular response to osmotic stress; negative regulation of TORC1 signaling; protein stabilization; transforming growth factor beta receptor signaling pathway; intracellular signal transduction; negative regulation of Wnt signaling pathway; peptidyl-threonine phosphorylation; positive regulation of receptor signaling pathway via STAT; protein phosphorylation; regulation of DNA-templated transcription; Wnt signaling pathway, calcium modulating pathway; cellular response to stress; MAPK cascade; regulation of signal transduction; signal transduction
Cellular component: cytoplasm; cytosol; nucleoplasm; nucleus
Genetic constraint (gnomAD): Loss-of-function variants: 5 observed, 34.18 expected, observed/expected ratio (o/e) 0.15, 90% interval 0.075 to 0.31. The upper end of that interval is the gene's LOEUF score, 0.31, which puts it in group 1 of 6, group 1 being the genes least tolerant of losing a copy. Missense variants: 303 observed, 451.58 expected, observed/expected ratio (o/e) 0.67, 90% interval 0.61 to 0.74. Synonymous variants: 155 observed, 166.47 expected, observed/expected ratio (o/e) 0.93, 90% interval 0.82 to 1.06.
Homologues: Orthologues: chimpanzee NLK (100% identical), guinea pig NLK (100% identical), macaque NLK (100% identical), pig NLK (100% identical), dog NLK (99% identical), mouse Nlk (99% identical), rabbit NLK (99% identical), tropical clawed frog nlk (96% identical), zebrafish nlk2 (95% identical), rat Nlkl1 (93% identical), Drosophila melanogaster nmo (63% identical), Caenorhabditis elegans lit-1 (56% identical), and 9 more. Paralogues in human: MAPK7 (35% identical), MAPK1 (28% identical), MAPK3 (28% identical), MAPK14 (27% identical), MAPK10 (26% identical), MAPK6 (26% identical), MAPK11 (26% identical), MAPK9 (25% identical), MAPK8 (24% identical), MAPK15 (24% identical), MAPK12 (24% identical), MAPK13 (24% identical), and 7 more.
Diseases named in the same sentence as NLK in open-access papers:
NLK is named in the same sentence as 64 diseases in open-access papers, as found by Europe PMC text mining. Sharing a sentence is not in itself a finding about the gene and the disease. The quoted sentences say what the papers report.
breast carcinoma (11 papers, 2013 to 2025). "Further studies are needed to define how inactive mutant of NLK can associate with HSP27 in breast cancer cells." (PMID 24816797, 2014). "The present study showed that induction of wild-type NLK in the human breast carcinoma cell line MCF-7 caused cell growth suppression and apoptosis induction." (PMID 23935942, 2013). "The underlying mechanism by which NLK regulates c-Myb expression remains to be elucidated; however, NLK’s role in human breast cancer development and progression by attenuating c-Myb activity makes it an attractive target for cancer therapy." (PMID 23935942, 2013). "To evaluate whether the HSP27 association with NLK in breast cancer cells may affect NLK localization, we treated cancer cells with siRNA against HSP27, and found that HSP27 depletion in MCF7 cells elicited NLK re-localization from the nucleus to the cytosol." (PMID 24816797, 2014). "The data suggest that NLK might be associated with the development of aggressiveness in breast carcinoma." (PMID 23935942, 2013). "Reduced NLK expression was closely associated with the breast cancer malignancy." (PMID 23935942, 2013). "For example, in human breast cancer cells, NLK has been reported to inhibit apoptosis by associating with heat shock protein, while in NSCLC, NLK has been shown to inhibit cancer progression and metastasis." (PMID 39348153, 2025). "In contrast, NLK is significantly downregulated in breast cancer tissues, and re-expression of NLK results in c-Myb downregulation, reduced proliferation, and increased apoptosis in MCF7 breast cancer cells." (PMID 38992436, 2024). "For instance, serine/threonine protein kinase NLK was demonstrated to localize in the nucleus of breast cancer cells and protect the cells from apoptosis." (PMID 34439480, 2021). "NLK-dependent phosphorylation of c-Myb in breast cancer and Wnt signaling has been demonstrated to facilitate rapid ubiquitination and subsequent proteasome degradation." (PMID 32620751, 2020). "In conclusion, our findings unveil a novel mechanism, by which HSP27 recognizes NLK in breast cancer cells and prevents NLK-mediated cell apoptosis." (PMID 24816797, 2014). "The present study provides evidence of a novel mechanism by which HSP27 recognizes NLK in the breast cancer cells and prevents NLK-mediated cell apoptosis." (PMID 24816797, 2014). "NLK was significantly downregulated in the breast cancer tissues compared to corresponding normal tissues." (PMID 23935942, 2013). "NLK expression was negatively correlated with Ki-67 expression (Spearman’s r = −0.743, P<0.001) in all of the analyzed breast cancer cases." (PMID 23935942, 2013). "To explore the relationship between the two molecules in human breast carcinoma progression and further characterize the relationship between NLK and c-Myb, we investigated their abundance in breast cancer cells by Western blot analysis." (PMID 23935942, 2013). "More studies are needed to address the possibility of other pathways regulating NLK function in breast cancer cells, which has been reported previously for other cell lines." (PMID 23935942, 2013). "In conclusion, NLK plays an antineoplastic role in breast cancer via regulating its target gene c-Myb." (PMID 23935942, 2013). "In this study, we used immunohistochemical analysis to assess NLK expression in breast carcinoma cases." (PMID 23935942, 2013). "NLK was mainly expressed in the nuclei, while c-Myb was expressed both in the cytoplasm and nuclei of breast cancer cells." (PMID 23935942, 2013). "Since we found no NLK mutations (K155 or T286) in four breast cancer cell lines and non-cancerous MCF10A cells, this indicates that these mutations alone are not responsible for NLK association to HSP27." (PMID 24816797, 2014). "Since we found no NLK mutations at lysine 155 or threonine 286 in breast cancer cell lines, this indicates that these mutations alone are not responsible for NLK association to HSP27." (PMID 24816797, 2014).
breast carcinoma (continued). "To investigate whether NLK overexpression would downregulate c-Myb levels in breast carcinoma cells, we transfected MCF-7 cells with pcDNA3.1-EGFP-NLK or an empty vector and measured NLK and c-Myb levels 48 hours after transfection." (PMID 23935942, 2013). "This is the first study showing that NLK is dysregulated in human breast carcinoma and suggesting that NLK might contribute to tumor cell growth and apoptosis." (PMID 23935942, 2013). "To determine whether there was a physiological or pathological relationship between the expression of NLK, c-Myb and the proliferation index Ki-67 in breast carcinoma specimens, we examined the levels of NLK, c-Myb and Ki-67 using immunohistochemical staining." (PMID 23935942, 2013). "Taken together, our observations supported the hypothesis that NLK might contribute to the progression of breast carcinoma as a regulator of c-Myb." (PMID 23935942, 2013). "Furthermore, we observed an inverse correlation between NLK and c-Myb expression in breast carcinomas, with low NLK expression being a poor prognostic factor." (PMID 23935942, 2013). "NLK has been shown to play a role in the induction of apoptosis in prostate cancer cells; however, whether this protein kinase has a function in breast cancer cell apoptosis remains unclear." (PMID 23935942, 2013). "We hypothesize that NLK might be involved in the degradation of c-Myb and that its target genes c-myc and bcl-2 might be potential prognostic factors for breast carcinoma." (PMID 23935942, 2013). "This study demonstrates the consequences of NLK dysregulation in human breast carcinoma." (PMID 23935942, 2013). "We hypothesize that the functional interaction between NLK and c-Myb has a critical role in breast carcinoma progression." (PMID 23935942, 2013). "In this study, we used immunohistochemical analysis to determine whether there is a strong negative association between NLK and cytoplasmic c-Myb in breast carcinoma specimens, and we compared those findings with clinical outcomes." (PMID 23935942, 2013). "NLK contributes to tumor cell growth through activation of the cell cycle transition in human hepatocellular carcinomas; however, whether this protein kinase has a function in breast cancer cell proliferation remains unclear." (PMID 23935942, 2013). "The members of the miR-23a ~ 27a ~ 24-2 cluster integrally inhibit the aggressiveness of breast cancer cells by targeting NCOA1, NLK, and RAP1B." (PMID 39112518, 2024). "In contrast to the endogenous NLK expressed in MCF10A, which was phosphorylated and catalytically active, NLK expressed in breast cancer cells showed to be unphosphorylated and catalytically inactive." (PMID 24816797, 2014). "In breast cancer cells, we noted that HSP27 localization was similar to NLK localization, and by confocal imaging, we confirmed co-localization of these two proteins in cancer cells." (PMID 24816797, 2014). "This was evident by stimulation of breast cancer cells with TNF-α, which promoted re-localization and accumulation of NLK in the cytoplasm." (PMID 24816797, 2014). "First, we examined the basal abundance of NLK and c-Myb in one normal human breast epithelial cell line (HBL-100) and two human breast cancer cell lines (MDA-MB-231 (ER-) and MCF-7 (ER+))." (PMID 23935942, 2013). "In breast cancer, NLK was found to be mainly localised in the nuclei of breast cancer cells compared to the cytosolic localisation in non-cancerous breast epithelial cells." (PMID 33276680, 2020). "The total levels of NLK in human breast cancer cells (MDA231 and MCF7) and non-cancerous human breast epithelial cells (MCF10A) revealed that NLK was significantly down-regulated in MDA231 but not in MCF7 compared to MCF10A cells." (PMID 24816797, 2014). "The endogenous nuclear localization of NLK in breast cancer cells did not change by cancer cells being transfected with NLK mutants, which prevent NLK activation." (PMID 24816797, 2014).
breast carcinoma (continued). "We found in the present study that endogenous NLK was localized predominantly in the nuclei of breast cancer cells, in contrast to a cytosolic localization in non-cancerous cells." (PMID 24816797, 2014). "In the present study we found that NLK was mainly localized in the nuclei of breast cancer cells, in contrast to a cytosolic localization in non-cancerous breast epithelial cells." (PMID 24816797, 2014). "In terms of NLK localization by subcellular fractionation, reduced NLK expression was observed in the cytosolic fractions of breast cancer cell lines, compared with non-cancerous human breast epithelial cells MCF10A." (PMID 24816797, 2014). "NLK immunoreactivity was observed in 42 (67.7%) of the breast cancer cases, whereas there was no detectable NLK immunoreactivity in 20 cases (32.3%)." (PMID 23935942, 2013). "We thank Dr. Kunihiro Matsumoto for WT-NLK, NLK-K155M, and NLK-T286V expression plasmids, Dr. Jody L Martin for WT-HSP27 expression plasmid, Dr. Lao Saal for proving us with the DNA from breast cancer and non-cancerous cell line, and Elise Nilsson for excellent technical assistance." (PMID 24816797, 2014). "Overexpression of wildtype NLK in the breast cancer cell lines MCF7, or non-cancerous human breast epithelial cells MCF10A, displayed a dominant cytosolic accumulation in all cells, whereas in the NLK mutants, the distribution was mainly located to the nuclei of MCF7 and MCF10A cells." (PMID 24816797, 2014).
hepatocellular carcinoma (11 papers, 2013 to 2024). A malignant tumor that arises from hepatocytes. "NLK expression is also reduced in prostate metastasis, hepatocellular carcinoma, and glioblastoma with less favorable clinical outcomes, suggesting NLK can serve as an oncogene or tumor suppressor, depending on cell context." (PMID 38992436, 2024). "While in gallbladder cancer, hepatocellular carcinoma and laryngeal cancer, NLK functioned as oncogene." (PMID 26084278, 2015). "Aberrant expression of NLK was correlated with proliferation and apoptosis in hepatocellular carcinoma, prostate cancer and colon cancer." (PMID 23935942, 2013). "However, although NLK was revealed to be overexpressed in hepatocellular carcinomas, depletion of NLK reduced cell growth, and did so by inhibiting the expression of cyclinD1 and CDK2, both essential for the mitogenic potential of tumor cells." (PMID 24816797, 2014). "NLK induces apoptosis and inhibits AR-mediated transcriptional activity in prostate cancer cells; however, it also contributes to tumor cell growth through the activation of the cell cycle transition in human hepatocellular carcinoma." (PMID 23935942, 2013). "NLK is a member of the mitogen-activated protein kinase family that regulates a wide range of transcription factors, and it is considered a tumor suppressor targeting Wnt/β-catenin signaling pathway in diverse cancers, such as ovarian cancer, glioma, and hepatocellular cancer." (PMID 38008713, 2023). "It is known that targeted disruption of NLK inhibits tumor cell growth by blocking cyclin D1 and CDK2 in human hepatocellular carcinoma." (PMID 35924150, 2022). "It is reported that miR-181 directly targets nemo-like kinase (NLK), an inhibitor of wnt/β-catenin signaling in Hepatocellular cancer." (PMID 24755295, 2014). "It has also been reported that targeted disruption of NLK inhibits tumor cell growth by simultaneous suppression of cyclin D1 and CDK2 in human hepatocellular carcinoma, which implies the anti-tumor activity of miR-101." (PMID 25337143, 2014).
colorectal cancer (6 papers, 2019 to 2024). A primary or metastatic malignant neoplasm that affects the colon or rectum. "Given that ELK/SRF promotes cell growth, we observed that NLK deficiency significantly inhibited cell cycle progression and cell growth in colorectal cancer." (PMID 35013153, 2022). "Altered expression of NLK is associated with cancer development and has been shown to be an independent prognostic factor in colorectal cancer." (PMID 31614935, 2019). "In colorectal cancer, NLK levels are significantly elevated compared to adjacent tissues and are correlated with tumor size and depth of invasion." (PMID 39097735, 2024). "The regulatory mechanism of NLK in the carcinomagenesis and progression of colorectal cancer (CRC) remains unclear." (PMID 34729110, 2021). "There is good evidence that miR-409-3p functions as a tumor suppressor in several cancers, for example, it is frequently downregulated in colorectal cancer, and acts as a tumor inhibitor by directly targeting the 3′ UTR of NLK." (PMID 32391354, 2020).
glioma (6 papers, 2015 to 2023). A benign or malignant brain and spinal cord tumor that arises from glial cells (astrocytes, oligodendrocytes, ependymal cells). "When we stratified glioma patients by NLK mRNA levels, a subset of glioma patients with top 25% of NLK mRNA survived significantly longer than the remaining patients, suggesting a potential association between NLK levels and patient survival." (PMID 26023737, 2015). "To further validate these findings, we surveyed the expression levels of NLK mRNA in glioma specimens utilizing Oncomine and Rembrandt databases and found that NLK mRNA levels are significantly lower in GBMs compared to non-tumor brain tissues." (PMID 26023737, 2015). "Previous studies indicated that NLK inhibits the β-catenin signaling pathway in glioma." (PMID 25823657, 2015). "NLK was presumed to be a tumor suppressor gene in ovarian cancer, glioma and prostate cancer." (PMID 26084278, 2015). "In addition, NLK was decreased in grade III and IV gliomas compared with grade II gliomas and normal brain tissues (P < 0.05)." (PMID 25823657, 2015).
non-small cell lung carcinoma (6 papers, 2015 to 2024). A group of at least three distinct histological types of lung cancer, including non-small cell squamous cell carcinoma, adenocarcinoma, and large cell carcinoma. "Abnormal expression of NLK is closely associated with the occurrence and progression of tumors, with high expression in laryngeal cancer, lung cancer, and cervical squamous cell carcinoma, but with low expression in non-small cell lung cancer, breast cancer, and ovarian cancer." (PMID 39097735, 2024). "Data in vitro and in vivo in non-small-cell lung cancer (NSCLC) cell lines showed that the biguanide—via inhibition of NLK expression—induced cell cycle arrest and significant reduction of the stem cell tumor population." (PMID 38610965, 2024). "ATF-2 activated the Wnt/Ca2+ pathway and promoted the expression of Wnt5a, Wnt11, CaMKII and NLK, which regulated the proliferation and invasion of non-small cell lung cancer cells, suggesting that Ca signaling is directly involved in malignant behavior of tumor cells." (PMID 39687904, 2024). "Here, we investigate a novel role of NLK and metformin in human non-small cell lung cancer (NSCLC)." (PMID 26503334, 2015). "In addition, it was also reported that metformin could target NLK (Nemo-like kinase) to inhibit non-small cell lung cancer (NSCLC) cell proliferation and stemness." (PMID 26957312, 2016).